RAB25 (RAB25, member RAS oncogene family)
Diseases named in the same sentence as RAB25 in open-access papers (continued):
Sharing a sentence is not in itself a finding about the gene and the disease.
cancer (continued). "In addition to Rab11 and Rab25, Rab21 is required for carcinoma-associated fibroblasts to promote invasion by cancer cells and facilitates integrin α5β1 accumulation for force-mediated matrix remodeling at the plasma membrane." (PMID 22121362, 2012). "Alterations in Rab25, Rab7, Rab5, and Rab11 have been reported to cause different types of cancers." (PMID 21143914, 2010). "We used this approach to demonstrate that the positioning of Rab25 vesicles to the PM is sufficient to generate nascent F-actin protrusions in cancer cells." (PMID 40614209, 2025). "Even more surprising was the observation that CAFs themselves exhibited increased invasiveness when in contact with Rab25‐high cancer cells." (PMID 40406984, 2025). "Mechanistically, CLIC3 acts in concert with Rab25 to recycle α5β1 integrin, facilitating cancer cell invasiveness by promoting integrin’s trafficking from late endosomes to the plasma membrane." (PMID 41465326, 2025). "Rab25 is upregulated in some cancers and can increase their aggressiveness when the lysosomal protein CLIC3 is co-upregulated to control a pathway that rescues integrins from lysosomes." (PMID 37232246, 2023). "RAB25 bound to Rab coupling protein (RCP) is known to increase cancer invasion and metastasis and the inhibition of RAB25-RCP is a potential therapeutic target." (PMID 36527824, 2023). "We found that there is an inverse relationship between methylation of the Rab25 promoter and its expression, where decreased methylation is correlated with increased gene expression, at both mRNA and protein levels across all cancer types." (PMID 35708998, 2022). "The Rab11 protein family (Rab11b and Rab25) have played a key role in cancer cell migration by regulating integrin recirculation at the migration front." (PMID 34141705, 2021). "A recent study showed that GRHL2 is a key player in EMP and other studies indicated that GRHL2 directly regulates EpCAM and RAB25 expression, which are correlated with cancer progression." (PMID 34771571, 2021). "Rab25 has diverse roles in the various types of cancers and functions as oncoprotein in bladder cancer, gastric cancer, lung cancer, whereas acts as tumor-suppressive protein in head and neck cancer, esophageal cancer, triple-negative breast cancer." (PMID 34868916, 2021). "Another example is Rab25, which functions as a prognostic indicator for breast, ovarian, kidney and other cancers." (PMID 34141705, 2021). "Overexpression of RAB25 was correlated with poor prognosis and aggressiveness of renal, lung, breast, ovarian and other cancers." (PMID 34056873, 2021). "Rab25 was regulated by different miRNAs in cancer progression, suggesting a possible miRNA-mediated mechanism in tumor biology." (PMID 34868916, 2021). "Intriguingly, several genes showing positive correlation in gene bodies have been previously linked to cancer, including MUC15, HEPACAM2, CA10, NRG1 and RAB25 (Mitra, Cheng & Mills, 2012)." (PMID 32832275, 2020). "As with Rab25, Rab11a has been reported to have both tumour-promoting and tumour-suppressing roles in cancer." (PMID 32842549, 2020). "Multiple clinical findings support the role of Rab25 as a prognostic marker for patients with several types of cancers such as breast, ovarian and renal cancer." (PMID 31973201, 2020). "In these cancers, Rab25 acts as an oncogene and promotes epithelial–mesenchymal transition (EMT) and metastasis." (PMID 32842549, 2020). "Out of these, 90 had balanced bimodal distributions including E-cadherin, Claudin7, and Rab25, indicating common pan-cancer oncogenic switches, while 82 were classified as rare transitions." (PMID 29293502, 2018). "Using a hierarchical network layout algorithm, E-cadherin was found downstream of Claudin7 and Rab25 concurrent with EMT3 preceding EMT1 in cancer cell lines." (PMID 29293502, 2018).
cancer (continued). "This review recapitulates our current knowledge of the role of Rab25 in cancer, including the involvement of Rab25 in cancer prognosis, cancer progression, functional mechanisms and future research directions." (PMID 28969096, 2017). "Rab25 is predominantly an oncogene, but it also acts as tumor suppressor in certain types of cancer." (PMID 28969096, 2017). "Elevated expression of Rab25 correlated with poor prognosis and tumor metastatic potential of cancer patients, suggesting Rab25 is a potential marker for cancer progression." (PMID 28969096, 2017). "Taken together, activation of growth-stimulating signaling pathways and suppression of apoptotic cell death pathways mediate the effect of Rab25 on enhancing cancer progression." (PMID 28969096, 2017). "Here, the authors develop all-hydrocarbon stabilized peptides targeting RAB25 and influencing the context-specificity phenotypes in cancer cell lines." (PMID 28939823, 2017). "It is indicated that Rab25 is a potential prognostic marker for patients with various types of cancer." (PMID 28969096, 2017). "Rab25, a small GTPase belongs to the Rab protein family, has a pivotal role in cancer pathophysiology." (PMID 28969096, 2017). "Taken together, better understanding of Rab25 function under different circumstances, together with development of Rab25 specific targeting agents, will be required for development of novel therapeutic strategy targeting Rab25 in cancer treatment." (PMID 28969096, 2017). "The role or Rab25 in promoting cancer metastasis is confirmed by in vitro experiments in which knockdown of Rab25 decreased cell migration and invasion of 786-O and A-498 RCC cells." (PMID 28969096, 2017). "Elevated expression of Rab25 was correlated with poor prognosis and aggressiveness of renal, lung, breast, ovarian and other cancers." (PMID 28969096, 2017). "In-depth study is needed to find out the downstream effectors that mediate the distinct function of Rab25 in cancer." (PMID 28969096, 2017). "Since Rab25 is involved in the control of vesicle trafficking and signaling pathways, it is frequently reported to have altered expression in cancer." (PMID 28969096, 2017). "Ras-related protein 25 (Rab25) functions either as an oncogene or a tumor suppressor with a cancer type-dependent manner." (PMID 28400705, 2017). "Biological and clinicopathological findings revealed that alteration of Rab25 level has high impact on cancer progression and patient survival." (PMID 28969096, 2017). "Rab25 was reported to initiate cancer formation, promote cell proliferation, suppress apoptotic cell death, enhance cell migration/invasion and increase drug resistance upon chemotherapy of various types of cancer." (PMID 28969096, 2017). "Reducing ZEB1 expression increases levels of ESRP1 and RAB25 in human cancer and vice versa, and in our study ZEB1 directly affected transcription of both genes." (PMID 26646320, 2016). "Such an effect on both cellular localisation and transcriptional control of GLUT1 by Rab25 has the ability to ensure cancer cell survival under nutrient stress conditions." (PMID 26967059, 2016). "Whole genome methylation data from The Cancer Genome Atlas project (TCGA) shows that Rab25 gene is indeed highly methylated in basal-like and normal-like tumors compared to luminal B tumors." (PMID 27259233, 2016). "It has been suggested that Rab25 promotes the cancer pathophysiological phenotype by regulating cellular ATP levels and glycogen stores that protect cancer cells from bioenergetic stress." (PMID 26967059, 2016). "In contrast, the slow growing tumors, with intact E-cadherin expression had comparable (to human luminal B cancer cell lines) levels of Rab25 reinforcing a strong cell lineage specific expression and function of Rab25." (PMID 27259233, 2016). "Rab25 has been found in high levels in a number of cancers and was shown to contribute to invasiveness of cancer cells by promoting integrin trafficking." (PMID 27005655, 2016).
cancer (continued). "Induction of HIF-1α was observed upon expression of Rab25 across a panel of cancer cell lines of different origins." (PMID 26967059, 2016). "In this report we demonstrate that Rab25 regulates HIF-1α protein expression in an oxygen independent manner in a panel of cancer cell lines." (PMID 26967059, 2016). "An explanation for the discrepancies is that the role of Rab25 in tumorigenesis is dependent on specific or a group of cancer type and on its interplay with cell-type specific effectors." (PMID 27716280, 2016). "Based on this finding, we suggest that palmitoylated cld7 and the vesicle transporter rab25 support cancer-initiating cell activities, possibly via the transfer of exosomes." (PMID 26054340, 2015). "It has been shown that Rab25 is involved in cancer progression by cell proliferation and fortification from apoptosis." (PMID 25815277, 2015). "This process, which occurs specifically in cancer cells, requires the concerted activities of Rab25 and chloride intracellular channel protein 3 (CLIC3)." (PMID 25663697, 2015). "Recently, the roles of several members of the Rab family in human cancer have drawn great attention, including Rab23 and Rab25." (PMID 26070933, 2015). "Expression of Rab25, which is located in the 1q amplicon present at high frequency in many cancer lineages, promotes cancer cell survival under multiple stress conditions." (PMID 25520884, 2013). "In the present study, we demonstrated that Rab25 plays a role in regulating OPG release providing a survival advantage for cancer cells in the presence of TRAIL." (PMID 25520884, 2013). "Expression of the Rab25 small G protein, which is a target of the 1q amplicon in multiple cancer lineages, is sufficient to increase cell survival under stress conditions including nutrient withdrawal, anoikis, UV-radiation, and paclitaxel." (PMID 25520884, 2013). "Critically, exogenous OPG mimicked the effects of Rab25 on cell death supporting the contention that Rab25-induced accumulation of OPG protects cancer cells from the effects of TRAIL." (PMID 25520884, 2013). "Rab25 shows highly restricted expression under normal physiological conditions but is upregulated in invasive cancer cell lines and metastatic tumor cells, and its elevated expression is further linked to the aggressiveness of breast and ovarian cancers." (PMID 22121362, 2012). "Further work will be necessary to define other key molecular components of the CLIC3-regulated recycling pathway, and to determine how these can dictate Rab25's capacity to promote or retard cancer progression." (PMID 22197222, 2012). "These discrepancies led us to further investigate the mechanisms by which Rab25 influences invasive behavior in vitro and the progression of cancer in vivo." (PMID 22197222, 2012). "Conversely, rab25 overexpression in cancer cell lines substantially suppressed cell invasion in vitro and tumor formation in vivo." (PMID 22920728, 2012). "In human colorectal adenocarcinomas, Rab25 functions as a tumor suppressor at independent cancer stages by regulating protein trafficking to cell surfaces." (PMID 21143914, 2010). "Furthermore, we report the first description of protein interaction networks formed by the cancer-relevant protein Rab25." (PMID 37232246, 2023). "In addition to these key cellular functions affected, we found that a reported tumor suppressor gene (RAB25) was hypermethylated and underexpressed in three out of four stages of cancer, via a deregulated FAK-Raf-MEK1/2-ERK signaling pathway." (PMID 37693315, 2023). "The expression measurements of mRNA with a slight difference are constantly higher than protein RAB25, resulting in a positive ratio of mRNA–protein in tumors, except when the mRNA rises to 9 and the protein amount stays between 0 and 2 in the cancer cell lines." (PMID 36360219, 2022). "Previous studies have shown that RAB10, RAB11A, RAB17, and RAB25 could promote cell proliferation in different cancers." (PMID 35154286, 2022).
cancer (continued). "The Rab25 gene is often hypermethylated, and its expression switched off in these cancers." (PMID 32842549, 2020). "Additionally, Rab25 plays a role in cancer cell survival through the inhibition of nutrient-stress induced apoptosis and autophagy." (PMID 31973201, 2020). "Re-expressing RAB25 might not only affect the migratory properties but could also lead to the sensitization of cancer cells to specific therapies." (PMID 30445998, 2018). "Another functional effect of RAB25 expression could be the induction of mesenchymal-to-epithelial transition (MET) at disseminated cancer cell secondary sites and promotion of colonization, as proposed by Mitra and colleagues." (PMID 30445998, 2018). "RAB25 expression is altered in many cancer types (e.g., breast, colorectal, ovarian and lung)." (PMID 30445998, 2018). "With the in vitro activity and cell penetration of optimized RFP stapled peptides confirmed, we next sought to determine whether RFP-mediated disruption of RAB25:FIP complexes would antagonize RAB25-mediated phenotypes in cancer cells." (PMID 28939823, 2017). "The function of Rab25 in cancer is, therefore, multifactorial and tumor type-specific." (PMID 28969096, 2017). "In this review, we recapitulate the current knowledge of Rab25 in cancer development and therapy." (PMID 28969096, 2017). "Finally, given the pro-tumorigenic role of RAB25 in several cancers, RFP14 represents a starting point for the development of therapeutics targeting RAB25 function in human cancers." (PMID 28939823, 2017). "Rab25 is recognized to play a crucial role in tumorigenesis and cancer progression." (PMID 28969096, 2017). "The most validated RAB25-dependent phenotype in cancer is cell migration." (PMID 28939823, 2017). "The creation of first-in-class chemical probes targeting these proteins would also enable mechanistic evaluation of the diverse roles of RAB25 in cancer as well as aid in unraveling the many signaling pathways involving RAB proteins in diverse biological contexts." (PMID 28939823, 2017). "Rab25 has been reported to both enhance and suppress cancer progression." (PMID 28969096, 2017). "Altered expression of Rab25 is commonly observed in various types of cancer." (PMID 28969096, 2017). "Rab25 overexpression and gene copy number amplification was reported in various types of cancer." (PMID 28969096, 2017). "A large majority of clinicopathological findings indicate the oncogenic role of Rab25 in cancer." (PMID 28969096, 2017). "Moreover, it is important to identify the mechanisms that lead to copy number amplification of RAB25 in order to find out the potential methods for cancer prevention." (PMID 28969096, 2017). "The function of Rab25 differs greatly in different types of cancer." (PMID 28969096, 2017). "Rab25 is, therefore, important in determining the metastatic ability of cancer cells." (PMID 28969096, 2017). "Rab25 functions either as an oncogene or a tumor suppressor with a cancer type-dependent manner." (PMID 28969096, 2017). "The goal of this study is to shed light and clarity on two distinct roles of Rab25 in cancer which could be converted as therapeutic opportunity while targeting the derailed endocytic machinery in cancers." (PMID 27259233, 2016). "Rab25 expression also correlates with cancer stem cell-like populations in a subset of cancers." (PMID 27259233, 2016). "Rab25's role in cancer is in some cases enigmatic as it could appear to act either as a cancer and metastasis promoter or a tumour suppressor, and we have previously suggested that its mode of action may depend on the availability of its effector RCP." (PMID 25472813, 2015). "Interestingly, in hormone receptor negative breast cancer rab25 expression is very low, but the small subpopulation of cancer initiating cells express rab25." (PMID 26054340, 2015).
cancer (continued). "Rab25 directs ligand-bound active α5β1 integrins to late endosomes and lysosomes, where, instead of degradation, the receptors undergo retrograde transport to the plasma membrane at the rear of cancer cells in a CLIC3-dependent pathway." (PMID 25663697, 2015). "RAB25 (member of RAS protein family) plays an important role in survival of cancer cells." (PMID 25699255, 2015). "Some Rabs, such as Rab1b, Rab4b, Rab10, Rab22a, Rab24, and Rab25, are dysregulated in many cancers." (PMID 24587032, 2014). "Increased OPG expression induced by Rab25 may provide a mechanistic advantage for cancer development and progression." (PMID 25520884, 2013). "In addition, a role has been proposed for Rab25/AKT-activated glycogen stores in promoting cancer cell survival through aerobic-glycolysis-mediated ATP synthesis, a crucial requirement for enhanced UPS function." (PMID 24358206, 2013). "In summary, increased OPG release in the presence of high endogenous Rab25 levels may provide a survival advantage for cancer cells and contribute to selection of tumors with elevated Rab25 levels." (PMID 25520884, 2013). "However, more attention has been paid to the roles of Rab GTPases in cancer in recent years, and several members of the Rab family such as Rab11 and Rab25 have been shown to be aberrantly expressed in various cancer types." (PMID 22121362, 2012). "There are conflicts in the literature as to whether Rab25 functions primarily as a promoter or suppressor of cancer." (PMID 22197222, 2012). "In those investigations, Rab25 overexpression correlated with the aggressiveness of the cancer." (PMID 21063400, 2011). "In particular, the role of Rab25 in cancer progression has been studied at great length." (PMID 21143914, 2010). "In addition, Rab25 promotes or blocks tumor growth through the chloride intracellular channel protein 3 protein which is necessary for Rab25-mediated integrin recycling from late endosomes/lysosomes and drive cancer progression." (PMID 35927755, 2022). "Furthermore, CLIC3 and Rab25 work together to promote cancer progression." (PMID 34721733, 2021). "Furthermore, Rab25 mRNA is increased in multiple other cancer types including ovarian, prostate, bladder, breast and liver cancers making it a highly relevant target for potential cancer therapies." (PMID 31973201, 2020). "Not surprisingly, Rab25 is implicated in driving migratory pathways in many cancers." (PMID 27259233, 2016). "These protrusions are dependent on the actin-polymerizing protein FMNL1, and Rab25 coordinates the activity of RhoA with the arrival of FMNL1 and integrin β1 cargos to form protrusions that promote invasive migration of cancer cells in the 3D matrix." (PMID 40614209, 2025). "Other amplicons, including those comprising genes for Rab GTPases (1q22, which contains RAB25, and 6p11, containing RAB23), drive cancer by impinging on vesicle trafficking." (PMID 40047887, 2024). "Subsequent studies showed that RCP and RAB25 play important roles in regulating intracellular trafficking of integrins and RTKs, including EphA2 and EGFR1, in ways that support cancer cell migration and invasiveness." (PMID 40047887, 2024). "RAB25, which has been described as acting primarily as a tumor suppressor in CRC primary tumors, but as an oncogene in other cancer subtypes, was present at high levels in all metastatic samples of patients I and II." (PMID 35565214, 2022). "Clathrin, caveolin, Rabs (Rab4, Rab5A, Rab1A, Rab2A) as well as their effectors (Rab25, Vav1, Rab coupling protein,cdc42, VSP39), can contribute to the processes of cancer cell survival and metastasis, and cancer stem cell emergence." (PMID 29409507, 2018). "Rab25 induces epithelial–mesenchymal transition and activates AKT/GSK-3β/Snail signaling to increase cancer cell invasion and metastasis." (PMID 30158579, 2018).